SOX4 (SRY-box transcription factor 4)
Diseases named in the same sentence as SOX4 in open-access papers (continued):
Sharing a sentence is not in itself a finding about the gene and the disease.
breast tumors (8 papers, 2018 to 2026). "In order to demonstrate the relationship between SOX4 expression and aberrant PI3K/Akt signaling, as well as the association between SOX4 expression and molecular subtype, we examined these relationships in human breast tumors." (PMID 33837205, 2021). "SOX4 has also been demonstrated to be a part of gene signatures associated with metastasis of breast tumors to the brain and lungs." (PMID 30507376, 2018). "Here, we show that SOX4 mediates breast tumor-progression through maintenance of fMaSC gene expression." (PMID 34584219, 2021). "Notably, single-cell RNA-seq of primary breast tumors confirmed co-expression of SOX4 and cell cycle regulators." (PMID 41639049, 2026). "To further explore whether SOX4 is required for regulating differentiation of PyMT breast tumors we analyzed expression of the luminal marker Keratin 8 (K8) and the basal marker Keratin 14 (K14)." (PMID 34584219, 2021). "Analyses of human breast tumors indicate that SOX4 mRNA is uniformly overexpressed in basal-like tumors relative to adjacent normal tissue along with the SWI/SNF catalytic subunit SMARCA4 and SMARCB1 SMARCC1, SMARCD2, and ACTL6A, which encode for the essential subunits of this complex." (PMID 33837205, 2021). "Together, these findings demonstrate that SOX4 can control multiple aspects of breast tumor biology, and show for the first time that SOX4 may regulate tumor angiogenesis in vivo." (PMID 30507376, 2018). "SOX4 is an oncogene that promotes PI3K/Akt signaling, angiogenesis, and resistance to cancer therapies in breast tumors; thus, SOX4 is a biomarker for PI3K-targeted therapy." (PMID 35906698, 2022). "As such, our data indicate that the SOX4-SMARCA4 complex may play an integral role in TNBC genesis and progression by activation of novel gene expression programs in this subset of breast tumors." (PMID 33837205, 2021). "In the SQ breast tumors, we observed significantly upregulated mRNA levels of the Oct3/4 regulatory network, including ONSS, and several other PTFs, including Nanog, Sall4, Sox2, Sox4, FoxA2, Gata6, Zic2 and HoxB7, as well as Oct3/4 isoform B, polycomb suppressors Bmi1, EzH2, Amigo and Dkk1." (PMID 37298091, 2023). "To further examine the role of ID4 in cancer stemness, we knocked down ID4 in MDA-MB-468 breast tumor cells using SMARTpool siRNAs, and tested the expression of a panel of stemness genes including Twist1, Twist2, Snail, Slug, BMP2, IRF1, SOX4, Foxk1 and Notch3." (PMID 36291790, 2022).
neuroblastoma (8 papers, 2013 to 2024). Neuroblastoma (NB) is the most common solid, extracranial childhood tumor. "A recent study has shown that several master regulators important in sympathoadrenal neural crest lineages, including PHOX2A/B, GATA2/3, HAND2, SOX4/11, and INSM112 form a CRC on which the neuroblastoma tumor cells are dependent for survival and growth." (PMID 38653778, 2024). "Thus, ATRA initiates a change in cell state of neuroblastoma cells corresponding to a shift from the adrenergic CRC to a new retino-sympathetic CRC, which includes RARA, HAND2, ISL1, TBX2, TBX3, MEIS1, and SOX4." (PMID 34669465, 2021).
diabetes (7 papers, 2011 to 2024). "Reduced SOX4 expression has been linked to an increased risk of diabetes due to its impairment of normal β-cell replication." (PMID 39498440, 2024). "In addition, increased SOX4 expression inhibits insulin secretion by upregulation of STXBP6 and increases the risk of diabetes." (PMID 35573654, 2022). "Next, we addressed the question whether regular intake of Metformin by diabetic cancer patients might have an impact on expression of SOX4 and other Wnt target genes in their tumor tissue." (PMID 29977599, 2018).
Intellectual disability (7 papers, 2023 to 2025). "Phenotypic features of all new patients described here match with those described previously in other patients with variants of SOX4 and include intellectual disability, developmental delay, and behavioural concerns." (PMID 36834931, 2023). "While our experiments provide further support for the pathogenicity of SOX4 loss-of-function (LOF) variants as a cause of syndromic intellectual disability (ID), our results also indicate incomplete penetrance associated with one variant." (PMID 36834931, 2023). "Here, we report the identification and functional investigation of three novel SOX4 variants in patients with developmental delay and intellectual disability." (PMID 36834931, 2023). "SOX4 variants have been recently described to cause a highly penetrant but heterogeneous disorder, with a phenotypic spectrum ranging from mild developmental delays and learning difficulties to intellectual disabilities with congenital anomalies." (PMID 38397148, 2024). "Mutations in SOX4 and SOX11 cause intellectual disability and other neurodevelopmental alterations, and variants in the TFAP2D locus are associated with bipolar disorder and emotional dysregulation." (PMID 39814878, 2025). "Furthermore, SOX4 and SOX11, members of the SoxC gene group, are both associated with neurodevelopmental delay and intellectual disability." (PMID 39057025, 2024).
myeloid leukemia (7 papers, 2006 to 2021). A clonal proliferation of myeloid cells and their precursors in the bone marrow, peripheral blood, and spleen. "In addition, Hoxa9 and Mzf1 involved in development of myeloid leukemia were up-regulated, while genes associated with differentiation, including Pax5 and Sox4, were down-regulated in both DKI and Dnmt3aR878H/+ groups." (PMID 31703632, 2019). "In fact, MEF2C was proposed to promote metastases development in pancreatic adenocarcinoma by inducing metalloproteinase (MMP) 10 transcription and to promote myeloid leukaemia, behaving as an oncogene by cooperating with the Sox4 gene." (PMID 33673112, 2021). "The Sox4 transcription factor and Evi1 cooperate to induce myeloid leukemia; and Evi1 was shown to bind to Sox4 promoter and regulate its gene expression, providing evidence of transactivation of Sox4 by Evi1." (PMID 24586749, 2014). "Sox4 has also been identified as a frequent insertional mutagenesis target in murine myeloid leukemias, further supporting a role of this gene in malignant transformation." (PMID 16600034, 2006). "A previous study reported that SOX4 could directly repress PU.1 expression, resulting in the blocked differentiation of myeloid leukemia cells in mouse models." (PMID 26673819, 2016). "Although the normal function of Sox4 in HSCs is not known, over-expression of Sox4 in mouse HSCs has recently been shown to cause myeloid leukemia and Sox4 is also a frequent insertional mutagenesis target in murine myeloid leukemias." (PMID 16600034, 2006).
cholangiocarcinoma (6 papers, 2013 to 2021). A carcinoma that arises from the intrahepatic biliary tree (intrahepatic cholangiocarcinoma) or from the junction, or adjacent to the junction, of the right and left hepatic ducts (hilar cholangiocarcinoma). "In cholangiocarcinoma, SOX4 is overexpressed and predicts poor prognosis." (PMID 33824274, 2021). "In previous studies, KCNQ1OT1 facilitated progression of cholangiocarcinoma (CCA) by sponging miR-140-5p and regulating SOX4 expression." (PMID 32377169, 2020).
chondrosarcoma (6 papers, 2018 to 2024). A malignant cartilaginous matrix-producing mesenchymal neoplasm arising from the bone and soft tissue. "Another miRNA, miR-30a, exhibits the ability to decrease tumor proliferation, migration, and invasion in chondrosarcoma by targeting the oncogenic SRY-related HMG box 4 (SOX4), which is involved in chondrocyte differentiation." (PMID 38542153, 2024). "Down-regulation of miR-30a leads to increased expression of SOX4, which cooperates with various transcription factors for the genesis of chondrosarcomas, such as c-MYC, E2F1, and E2F4, suggesting tumor progression." (PMID 38542153, 2024). "In chondrosarcoma, SOX4 overexpression served as a prognostic marker in patients with low histologic grade chondrosarcoma, and miR-30a was inversely correlated with SOX4 expression in chondrosarcoma cases." (PMID 37057210, 2023). "In line with this, in chondrosarcoma cell lines miR-129-5p repressed WNT/β-catenin signaling by targeting SOX4 which repressed proliferation and invasion." (PMID 29361725, 2018). "Also, miR-129-5p, which targets SOX4, was significantly downregulated in human chondrosarcoma tissues, while SOX4 protein was activated." (PMID 29361725, 2018). "Indeed, this imbalance of SOX9 and SOX4 may contribute to the incomplete chondrogenic differentiation and persistent proliferation of chondrosarcomas." (PMID 29361725, 2018). "Notably, SOX4 and runt related transcription factor 2 (RUNX2), which are both implicated in regulation of chondrogenesis and osteogenesis, are targets of miR-30a, which is progressively downregulated with increasing chondrosarcoma grade, leading to a relative overexpression of SOX4 and RUNX2." (PMID 29361725, 2018).
osteoarthritis (6 papers, 2020 to 2026). A noninflammatory degenerative joint disease occurring chiefly in older persons, characterized by degeneration of the articular cartilage, hypertrophy of bone at the margins and changes in the synovial membrane. "Several transcription factors have been implicated in the onset and progression of osteoarthritis, including Runx2, C/EBPβ, HIF2α, Sox4, and Sox11." (PMID 32079226, 2020). "The latest research has shown that the SOX4 can participate in the pathological changes of osteoarthritis cartilage by regulating ADAMTS4 and ADAMTS5." (PMID 34006298, 2021). "It was found in a mouse model that SOX4 mRNA expression was increased in the cartilage of the osteoarthritis patients, resulting in articular cartilage destruction through adenovirus infection." (PMID 34006298, 2021). "A previous study has revealed that miR‐31‐5p inactivates mTORC1 by directly targeting SOX4 to affect apoptosis and autophagy of chondrocytes, suggesting that SOX4 may play a protective role in the progression of osteoarthritis." (PMID 39500626, 2024). "Moreover, SOX4 was suggested to be involved in osteoarthritis onset, where its mRNA expression increased in the cho cartilage of patients with osteoarthritis compared to the control subjects." (PMID 36835620, 2023). "Furthermore, expression of SOX4 and SOX11 was associated with the destruction of cartilage in patients with osteoarthritis, suggesting the importance of these transcription factors in both the onset and progression of osteoarthritis." (PMID 32079226, 2020). "Unlike SOX4, which is upregulated in almost all of the studies investigating its role in arthritis disease, SOX11 is downregulated in some studies and upregulated in others during osteoarthritis progression." (PMID 36835620, 2023).
pancreatic ductal adenocarcinoma (6 papers, 2015 to 2025). An infiltrating adenocarcinoma that arises from the epithelial cells of the pancreas. "Nevertheless, the different functions of SOX4 in TGF‐β‐driven tumourigenesis or apoptosis in pancreatic ductal adenocarcinoma demonstrate its multiple and various effects based on context." (PMID 35522942, 2022). "This was interesting, as SOX4 is traditionally associated with tumorigenicity; however, it was found that in a pancreatic ductal adenocarcinoma model, SOX4 induced apoptosis and it was only upon SOX4 complexing with KLF5 (upon downregulation of SNAI1) that there was increased tumorigenesis." (PMID 34680503, 2021). "According to the Kaplan–Meier analysis results, high SOX4 expression was significantly correlated with poor OS in LIHC, pancreatic ductal adenocarcinoma, and SARC." (PMID 37958409, 2023). "In addition, miR-129-2 and miR-335 are suppressed in human pancreatic ductal adenocarcinoma (PDAC) and the miR-129-2/miR-335/Sox4/semaphorin-plexin regulatory axis plays a role in tumorigenesis." (PMID 25970172, 2015).
bladder tumors (5 papers, 2008 to 2025). "For instance, the gain&CN-LOH hotspot #1, affecting E2F3 and SOX4, is the most frequent aberration in bladder tumors." (PMID 38473323, 2024). "This study conducted in 2360 clinically annotated bladder tumors using tissue microarray found unexpectedly, a correlation (p < 0.05) between strong SOX4 expression and increased patient survival." (PMID 30072631, 2018). "SOX4 gene expression was increased 2.2-times in bladder tumors compared to normal tissue by immunohistochemistry and real-time PCR." (PMID 30072631, 2018). "Among them, 13 genes, including AHR, BCL2L1, CCND1, KRAS, SOX4, MYC, and E2F family genes, were previously reported to have increased expression in BC tissue, and their alterations, either through amplification or upregulation, are linked with bladder tumor initiation or progression." (PMID 40801146, 2025). "SOX4, another SOX family member, is overexpressed in bladder tumors harboring the genomic 6p22 amplification." (PMID 32427884, 2020). "We confirmed that SOX4, but not SOX2, was mainly amplified in primary bladder tumors." (PMID 32427884, 2020).
oral squamous cell carcinoma (5 papers, 2015 to 2024). "Specifically, SNHG17 upregulates PAX6 to facilitate the development of oral squamous cell carcinoma, stimulates SOX4 to promote the epithelial-mesenchymal transition in ESCC cells, and activates H2AX-associated signaling pathways to promote the development of renal cell carcinoma." (PMID 37231440, 2023). "IL-6 could promote proliferation via JAK2/STAT3/SOX4 pathway in oral squamous cell carcinoma cells." (PMID 39963655, 2024). "This study evaluated whether SOX4 affects oncogenic behavior and chemoradiotherapy response in head and neck squamous cell carcinoma (HNSCC) cells, and documented the relationship between its expression and prognosis in oral squamous cell carcinoma (OSCC)." (PMID 26555193, 2015).
osteoporosis (5 papers, 2021 to 2024). A condition of reduced bone mass, with decreased cortical thickness and a decrease in the number and size of the trabeculae of cancellous bone (but normal chemical composition), resulting in increased fracture incidence. "On the other hand, investigating the differentially expressed genes (DEG) in a cohort of postmenopausal women revealed that SNPs in the MMP9 and SOX4 genes were associated with an increased risk of osteoporosis." (PMID 36835620, 2023). "By conducting a case-control study, we found that the SOX4 gene rs79958549 A allele, rs139085828 A allele, and rs201335371 C allele were significantly associated with an increased risk of osteoporosis." (PMID 34006298, 2021). "The risk of osteoporosis in the carriers of A allele at SOX4 rs79958549 was 5.40 times that in the carriers of the G allele (95% CI 3.25–8.96, P < 0.01)." (PMID 34006298, 2021). "First, the molecular mechanism of the SOX4 gene rs79958549, rs139085828, and rs201335371 related to osteoporosis risk needs to be further studied." (PMID 34006298, 2021). "The risk of osteoporosis in the carriers of the T allele at SOX4 rs201335371 was 0.54 times that in the carriers of the C allele (95% CI 0.43–0.69, P < 0.01)." (PMID 34006298, 2021). "We also found that the A-A-C haplotype formed by rs79958549, rs139085828, and rs201335371 of SOX4 gene was associated with an increased risk of osteoporosis, and the G-G-T haplotype was associated with a reduced risk of osteoporosis." (PMID 34006298, 2021). "The SOX4 gene SNPs rs79958549, rs139085828, and rs201335371 loci were significantly associated with osteoporosis risk." (PMID 34006298, 2021). "The rs79958549, rs139085828, and rs201335371 loci of the SOX4 gene and their interaction with environmental factors were associated with the risk of osteoporosis." (PMID 34006298, 2021). "The risk of osteoporosis in the carriers of the A allele at SOX4 rs139085828 was 1.68 times that in the carriers of the G allele (95% CI 1.45–1.85, P < 0.01)." (PMID 34006298, 2021). "We found that the SOX4 gene SNPs rs79958549, rs139085828, and rs201335371 are significantly associated with osteoporosis risk." (PMID 34006298, 2021). "Moreover, based on a systematic PubMed database search, SOX4 has been suggested to be among a set of five genes which should be further validated for their predictive, diagnostic, and clinical value in osteoporosis." (PMID 36835620, 2023). "The SOX4 gene rs79958549, rs139085828, and rs201335371 A-A-C haplotype (OR = 5.14, 95% CI 2.45–10.57, P < 0.01) were associated with increased risk of osteoporosis and G-G-T haplotype was significantly associated with decreased risk of osteoporosis (OR = 0.48, 95% CI 0.38–0.62, P < 0.01)." (PMID 34006298, 2021). "This study aimed to explore the correlation between the SRY-related high-mobility-group box gene 4 (SOX4) 3′ untranslated region (UTR) single nucleotide polymorphism (SNP) and osteoporosis susceptibility." (PMID 34006298, 2021). "In line with this, in a study exploring the correlation between the SOX4 gene 3′ (UTR) SNP and osteoporosis susceptibility, three SNPs loci, rs79958549, rs139085828, and rs201335371, at the SOX4 gene were found to be significantly associated with the risk of osteoporosis." (PMID 36835620, 2023). "Related to this, the single nucleotide polymorphism (SNP) in the 3′ UTR was found to be responsible for susceptibility to another common skeletal system disease osteoporosis, suggesting that the 3′ UTR region is involved in regulating SOX4 gene expression during inflammatory diseases." (PMID 36835620, 2023). "Furthermore, the potential role of SOX4 in the occurrence and development of osteoporosis needs to be confirmed by both in vitro and in vivo research." (PMID 34006298, 2021).
osteoporosis (continued). "The SOX4, SOX11 and SOX12 (SOXC) transcription factors were previously shown to control many developmental processes, including skeletogenesis, and SOX4 was linked to osteoporosis, but how SOXC control adult bone mass remains unknown." (PMID 38580651, 2024). "Interestingly, it was reported that single nucleotide polymorphism (SNP) in the untranslated region (UTR) lead to osteoporosis susceptibility, suggesting an important role for the 3’ UTR in the regulation of SOX4 gene expression in other diseases associated with inflammation." (PMID 35529852, 2022). "However, the specific mechanism of SOX4 in the development of osteoporosis remains unclear." (PMID 34006298, 2021).
pulmonary fibrosis (5 papers, 2019 to 2025). Chronic progressive interstitial lung disorder characterized by the replacement of the lung tissue by connective tissue, leading to progressive dyspnea, respiratory failure, or right heart failure. "In the lung of BLM-induced pulmonary fibrosis mice, SOX4 and COL1A1 expression was significantly upregulated." (PMID 30796204, 2019). "In BLM-induced pulmonary fibrosis mice, circHIPK3 silencing significantly decreased SOX4 and COL1A1 expression." (PMID 30796204, 2019). "Similarly to cardiac fibrosis, circHIPK3 increases the expression levels of SOX4 and COL1A1 by binding miRNA-338-3p in pulmonary fibrosis and thus promoting the progress of pulmonary fibrosis." (PMID 33693013, 2021).